MIR208A (microRNA 208a)
Synonyms: hsa-mir-208; hsa-mir-208a; MIR208; MIRN208; MIRN208A; miRNA208
Gene: MicroRNA gene on chromosome 14 (23,388,596 to 23,388,666, reverse strand). Ensembl gene ENSG00000199157.
Gene Ontology:
Biological process: miRNA-mediated post-transcriptional gene silencing
Homologues: Orthologues: chimpanzee ptr-mir-208a (100% identical), pig MIR208A (100% identical), guinea pig MIR208A (99% identical), macaque mml-mir-208a (99% identical), mouse Mir208a (96% identical), dog MIR208A (92% identical), tropical clawed frog xtr-mir-208 (72% identical), rat Mir3546 (69% identical). Paralogues in human: MIR208B (59% identical).
Diseases named in the same sentence as MIR208A in open-access papers:
MIR208A is named in the same sentence as 3 diseases in open-access papers, as found by Europe PMC text mining. Sharing a sentence is not in itself a finding about the gene and the disease. The quoted sentences say what the papers report.
congenital heart disease (1 paper, 2014). A heart disease that is present at birth. "Mir208a may also play a pivotal role in the formation of cardiac fibrosis in congenital heart disease, not just in acquired heart disease." (PMID 24392114, 2014).
MIR208A also shares sentences with these, for which no sentence is quoted: cardiac hypertrophy (1 paper); left ventricular hypertrophy (1).